FCGR3B (Fc gamma receptor IIIb)
Diseases named in the same sentence as FCGR3B in open-access papers (continued):
Sharing a sentence is not in itself a finding about the gene and the disease.
clear cell renal carcinoma (1 paper, 2022). A malignant epithelial neoplasm of the kidney characterized by the presence of lipid-containing clear cells within a vascular network. "In tumor tissue samples from patients with clear cell renal cancer, the predominant production of the FCGR3A mRNA was observed in comparison with the FCGR3B mRNA." (PMID 37064811, 2022).
co-infection (1 paper, 2013). "In this study we investigated whether CNV of FCGR2C, FCGR3A and FCGR3B as well as the HNA1 allotype of FCGR3B is associated with HIV load, response to highly-active antiretroviral therapy (HAART) and co-infection with TB." (PMID 24250791, 2013). "In this study we investigated whether copy number variation of FCGR2C, FCGR3A and FCGR3B as well as HNA1 allelic variation of FCGR3B is associated with HIV load, response to HAART and co-infection with TB in two African populations." (PMID 24250791, 2013).
coronary heart disease (1 paper, 2020). "CD163 and FCGR3B were both linked to cardiovascular disorder of the myocardium and coronary heart disease." (PMID 31900413, 2020).
Cryptococcal meningitis (1 paper, 2012). Meningeal inflammation produced by cryptococcus neoformans, an encapsulated yeast that tends to infect individuals with acquired immunodeficiency syndrome and other immunocompromised states. "Distribution of FCGR2A, FCGR3A, FCGR3B, FCGR2B genotypes in patients with cryptococcal meningitis and controlsa." (PMID 22879986, 2012). "In this case control genetic association study, we genotyped four functional polymorphisms in low-affinity FcγRs, including FCGR2A 131H/R, FCGR3A 158F/V, FCGR3B NA1/NA2, and FCGR2B 232I/T, in 117 patients with cryptococcal meningitis and 190 healthy controls by multiplex SNaPshot technology." (PMID 22879986, 2012).
cryptococcosis (1 paper, 2012). An acute or chronic, localized or disseminated infection by Cryptococcus neoformans. "Meletiadis and colleagues genotyped FCGR2A 131H/R, FCGR3A 158F/V and FCGR3B NA1/NA2 in 103 cryptococcosis patients and 395 healthy controls." (PMID 22879986, 2012).
cytomegalovirus infection (1 paper, 2025). A herpesvirus infection caused by Cytomegalovirus. "One patient, with a preceding cytomegalovirus infection, was identified with three copies of parts of both FCGR3A and FCGR3B and three copies of the entire FCGR2C and HSPA7 genes, suggestive of a novel CNR (CNR5)." (PMID 40593358, 2025). "In the present study, we identified a unique case of a GBS patient with a preceding cytomegalovirus infection who had three copies of parts of FCGR3A and FCGR3B, along with three copies of the entire FCGR2C and HSPA7 genes." (PMID 40593358, 2025).
eosinophilic granulomatosis with polyangiitis (1 paper, 2020). Eosinophilic granulomatosis with polyangiitis (EGPA), previously known as Churg-Strauss syndrome, is a systemic vasculitis of small-to medium vessels, characterized by asthma, transient pulmonary infiltrates, and hypereosinophilia. "FCGR3B is associated with innate immune system-related disease, including neonatal alloimmune neutropenia and eosinophilic granulomatosis with polyangiitis." (PMID 32596394, 2020).
glioma (1 paper, 2024). A benign or malignant brain and spinal cord tumor that arises from glial cells (astrocytes, oligodendrocytes, ependymal cells). "CLIC4 expression levels were positively correlated with specific markers of macrophages (CD80, CD86, MRC1), neutrophils (FCGR3A, FCGR3B), eosinophils (SIGLEC8, IL3RA), T cells (CD3D, CD4), CD8+ T cells (CD8A, CD8D), NK cells (NCAM1), and B cells (CD19) in glioma." (PMID 39595145, 2024).
Granuloma (1 paper, 2025). A compact, organized collection of mature mononuclear phagocytes, which may be but is not necessarily accompanied by accessory features such as necrosis. "A diverse array of innate immune cells, including mast cells (MC) (cluster 20: HDC, CPA3, KIT), dendritic cells (DC) (cluster 23: CLNK, WDFY4, FLT3), neutrophils (FCGR3B, FFAR2, CSF3R), and macrophages (CD68, CD163, C1QA/B/C), was also present in these granulomas." (PMID 40772762, 2025).
head and neck squamous cell carcinoma (1 paper, 2023). A squamous cell carcinoma that arises from any of the following anatomic sites: lip and oral cavity, nasal cavity, paranasal sinuses, pharynx, larynx, and salivary glands. "Therefore, the biological function of FCGR3B in head and neck squamous cell carcinoma (HNSCC) may be related to the immune system." (PMID 37670814, 2023).
IgA nephropathy (1 paper, 2020). "However, in this current study, we did not carry out mechanistic study on the direct evidence that could elucidate the interaction between lncRNA-G21551 and FCGR3B and the mechanisms involved in IgA nephropathy." (PMID 32234013, 2020).
kidney failure (1 paper, 2023). An acute or chronic condition that is characterized by the inability of the kidneys to adequately filter the blood. "FCGR3B, also known as CD16b, was also found to be related to kidney failure, especially with regard to antibody-triggered microcirculation inflammation after kidney transplantation." (PMID 37510279, 2023).
macrophage activation syndrome (1 paper, 2021). A complication of rheumatic disease that is caused by excessive activation and uncontrolled proliferation of T lymphocytes and well-differentiated macrophages. "Based on the abundance of FCGR3B upregulated MoAMs, it is possible that dysregulated macrophage response to SARS-CoV-2 infections may promote injury to the host tissue due to macrophage activation syndrome or serve as a Trojan horse, enabling specific viral anchoring to the pulmonary parenchyma." (PMID 34458692, 2021).
metastatic carcinoma (1 paper, 2020). A carcinoma which has spread from the original site of growth to another anatomic site. "Meanwhile, FCGR3B may be a helpful prognostic tool for patients with metastatic carcinoma." (PMID 32596394, 2020).
neuroblastoma (1 paper, 2021). Neuroblastoma (NB) is the most common solid, extracranial childhood tumor. "This analysis revealed that 1.918 of the 18.469 differentially expressed neuroblastoma transcripts were neutrophil-related, which included highly specific neutrophil markers such as FCGR3B, FPR1, S100A8/9, and SIGLEC9, among others." (PMID 34503071, 2021).
parasitemia (1 paper, 2022). "Only the haplotype 108C-114T-194A-233C-244A-316A (that differs from FCGR3B*02 only in 194 A > G) was associated with both high numbers of infections and high levels of parasitemia (p = 0.011 and p = 0.0001, respectively)." (PMID 36499205, 2022). "In contrast, 108C-114T-194G-233C-244G-316A (FCGR3B*06) was the unique combination of FCGR3B SNPs associated with both low numbers of infections and low levels of parasitemia (p = 0.018 and p = 0.043, respectively)." (PMID 36499205, 2022). "A reduced risk of malaria infections and low parasitemia were related to the carriages of the FCGR3B 108C-114T-194G-233C-244G-316A (FCGR3B*06), FCGR3B 108C–114T–194G–233A–244A–316A (FCGR3B*03 encoding for FcgRIIIB-SH) haplotypes and FCGR3B 297 TT genotype." (PMID 36499205, 2022). "High parasitemia and increased malaria infections were observed in infants carrying the FCGR3B*05 108C-114T-194A-233C-244A-316A haplotype." (PMID 36499205, 2022). "In conclusion, the present study showed that the FCGR3B 194AA genotype was associated with a higher risk of malaria infection and low IgG levels to GLURP-R0 and MSP3, while the FCGR3B 297 T-allele was associated with a reduced risk of P. falciparum infections and low parasitemia." (PMID 36499205, 2022).
pulmonary TB (1 paper, 2024). "A 6-protein diagnostic panel, comprising FETUB, FCGR3B, LRG1, SELL, CD14, and ADA2, differentiated patients with pulmonary TB from healthy controls and patients with other respiratory infections with high sensitivity and specificity in both cohorts." (PMID 38512356, 2024). "Four proteins, FCGR3B, FETUB, GGH, and SERPIND1, were present at significantly higher levels in the serum of pulmonary TB patients than both HCs and ORI cases, thereby exhibiting a high degree of specificity for TB." (PMID 38512356, 2024).
renal carcinoma (1 paper, 2022). A carcinoma arising from the epithelium of the renal parenchyma or the renal pelvis. "The aim of the study was to assess the capabilities of mRNA genes encoding CD16a (FCGR3A) and CD16b (FCGR3B) proteins in tumor samples from patients with renal cancer, and characterize the tumor process in relation to clinical and morphological factors." (PMID 37064811, 2022). "The aim of the study was to assess the capabilities of mRNA genes encoding CD16a (FCGR3A) and CD16b (FCGR3B) in tumor samples from patients with renal cancer, and characterize the tumor process in relation to clinical and morphological factors." (PMID 37064811, 2022). "There is rather limited information on the interaction between the levels of mRNA genes encoding CD16a (FCGR3A) and CD16b (FCGR3B) in a tumor, and clinic and morphological factors determining a cancerous disease course including renal cancer." (PMID 37064811, 2022).
tumor (23 papers, 2014 to 2025). "FCGR3A/FCGR3B emerged as a potentially druggable gene, predominates as a risk prognostic factor in most cancers, and is closely related to tumor immune-related pathways." (PMID 38339034, 2024). "In short, the results above suggested that mRNA expressions of FcγRs (except for FCGR3B) were positively correlated with individual tumor stages or cancer grades of patients." (PMID 35372055, 2022). "mRNA of the FCGR3A gene was detected in all tumor tissue samples under study; in contrast, mRNA of the FCGR3B gene was found only in 92.0% (115/125) of cases." (PMID 37064811, 2022). "In both tumor and normal lung tissue of all core atlas samples, the neutrophil cluster (FCGR3B, CSF3R, CXCR2, and G0S2) comprised 8,468 cells with overt low mRNA counts." (PMID 36368318, 2022). "Potentially FCGR3B CNV can be used as a new biomarker for cancer immunotherapy, where patients can be stratified with likelihood of benefitting from therapy when patients have a lower FCGR3B CNV combined with the right tumor antigens (e.g., HER2/Neu or EGFR)." (PMID 30761158, 2018). "Moreover, the expression level of FCGR3B was significantly different between tumor grades, T and N stages." (PMID 37670814, 2023). "The results showed that the mRNA levels of FCGR1A/B/C and FCGR3A were correlated with the tumor stages of ccRCC patients, whereas the mRNA levels of FCGR2A/B/C and FCGR3B did not markedly differ among tumor stages." (PMID 35372055, 2022). "The reason why the mRNA expression of FCGR2A/B/C and FCGR3B in ccRCC did not appear to be significantly different among tumor stages may be their unique roles in anti-tumor immunity." (PMID 35372055, 2022).
infection (8 papers, 2012 to 2025). The state of being infected such as from the introduction of a foreign agent such as serum, vaccine, antigenic substance or organism. "Among the FCGR3B SNPs studied, the results showed a high number of malaria infections associated with the carriage of FCGR3B 194AA (p = 0.027), while the FCGR3B 194 G-allele was related to a low risk of infection (p = 0.029)." (PMID 36499205, 2022). "There is some evidence of a relationship between FCGR3B and susceptibility to infection to support this theory, but the data are contradictory." (PMID 22309893, 2012). "Future research should explore these relationships further as well as consider whether low FCGR3B CN increases the risk of infection in the context of immunosuppressive disease-modifying therapy." (PMID 22309893, 2012). "Upregulation of genes such as Fc Gamma Receptor IIIb (FCGR3B) and Selectin L (SELL, L-selectin) was noted in moderate cases, highlighting neutrophils’ role in adhesion and migration, facilitating their accumulation at the infection site." (PMID 39928675, 2025).
renal disease (2 papers, 2012 to 2013). "Low FCGR3B CN was also increased in frequency in patients with active renal disease (characterized by proteinuria with active urinary sediment) (25 versus 6.4%, P = 0.03)." (PMID 23864940, 2013).
cardiovascular diseases (1 paper, 2020). "Two of the proteins in the NLRC5 network (CD163 and FCGR3B) were also linked to cardiovascular diseases." (PMID 31900413, 2020).
FCGR3B also shares sentences with these, for which no sentence is quoted: cancer (9 papers); Wegener's granulomatosis (4); asthma (3); glomerulonephritis (3); Addison's disease (2); Cirrhosis (2); Crohn disease (2); diabetes (2); giant cell arteritis (2); Graves disease (2); idiopathic pulmonary fibrosis (2); infectious disease (2); lung carcinoma (2); melanoma (2); non-small cell lung carcinoma (2); ANCA-associated vasculitis (1); anemia (1); anti-glomerular basement membrane antibody disease (1); Arthritis (1); autoimmune liver diseases (1); blood cancers (1); bullous pemphigoid (1); colorectal neoplasm (1); cystic fibrosis (1); depression (1); dermatomyositis (1); fragile X syndrome (1); head and neck neoplasm (1); heart failure (1); hematopoietic cancers (1).
A further 17 diseases each share a sentence with FCGR3B in 1 paper.